CXCR4 (C-X-C motif chemokine receptor 4)
Diseases named in the same sentence as CXCR4 in open-access papers (continued):
Sharing a sentence is not in itself a finding about the gene and the disease.
cancer (continued). "Interestingly, our results demonstrated that downregulation of CXCR4 is responsible for the “loss of adhesion,” one of the most important events responsible for the cancer cell metastases." (PMID 25114911, 2014). "High expression of CXCR4 was associated with carcinoma, migration, proliferation and metastasis." (PMID 25162584, 2014). "Increased CXCR4 expression is associated with aggressive cancer behavior." (PMID 23497290, 2013). "The CXCL12/CXCR4 signaling axis has been implicated in both cancer metastases and HIV-1 infection." (PMID 23202899, 2012). "This is important as overexpression of CXCR4 is associated with cancer development and metastasis." (PMID 22318730, 2012). "Next, because recent data have demonstrated that in some cancers there exists a subpopulation of migrating CSCs responsible for cancer metastasis and CXCR4 has been reported to be associated with the cancer cell metastasis phenotype, CD133+CXCR4+ cells were also detected by flow cytometry." (PMID 22871210, 2012). "In addition, increased CXCR4 expression has been observed in several types of cancer and is frequently associated with increased metastasis and poor prognosis." (PMID 21949786, 2011). "CXCL12/CXCR4 signaling has become increasingly implicated with various human cancers." (PMID 21949786, 2011). "The central role of CXCR4 in cancer metastasis also raises the question of whether CXCR4 can serve as an important diagnostic target in the detection and treatment of cancer." (PMID 21110890, 2010). "The chemokine receptor CXCR4 is implicated in the metastasis of various cancers." (PMID 21110890, 2010). "The chemokine and bone marrow-homing receptor CXCR4 is implicated in metastases of various cancers." (PMID 19508713, 2009). "Therefore,rosiglitazone and its analogues act through PPARγ to cause substantial andpersistent suppression of CXCR4 on cancer cells." (PMID 18779872, 2008). "Thus, blocking CXCL12 or MAPK may prevent the effects of CXCL12 / CXCR4 axis hence reversing the persistent pain associated with cancer." (PMID 39641645, 2024). "Furthermore, the expression level of CXCR4 has been linked to cancer progression and resistance to radio-/chemotherapy, indicating that it may also be a valuable prognostic biomarker for use in the molecular imaging of cancer growth, metastasis, and relapse." (PMID 39204345, 2024). "The results obtained in this study may seem controversial in comparison to previously published results elsewhere, in which MRP2, CXCR4, and PD-L1 were reported to be associated with the poor prognosis of patients with various cancers when expressed at high levels." (PMID 37444550, 2023). "Furthermore, CXCR4 overexpression is associated with poor prognosis in many cancer subtypes." (PMID 35630915, 2022). "Moreover, we found that enhancing CXCR4 signaling activity leads to the enrichment of several cancer-associated pathways, revealing that hyperactivated CXCR4 signaling might thereby predispose B cells for malignant transformation." (PMID 34363012, 2021). "In addition, the underlying mechanisms by which CXCR4 involved in regulating cancer progression are complicated, and competing endogenous RNA (ceRNA) mechanisms may be the reason." (PMID 34180759, 2021). "Thus, HST likely enhanced OUM tissue repair through oral keratinocyte migration upon MAPK and CXCR4 activation and may be useful in patients with cancer-associated OUM." (PMID 31953420, 2020). "In addition, CXCR4 overexpression promotes tumorigenesis and its expression and activity are associated with cell proliferation, invasion, migration, inflammation, angiogenesis, and metastasis in several cancer models." (PMID 32110952, 2020). "In this context, an autocrine regulatory loop between CXCL12 and CXCR4 can be hypothesized also for NETs, since evidence in other cancers suggests that persistent ligand stimulation causes CXCR4 degradation, as well as epigenetic regulation of the entire molecular synapse." (PMID 28186979, 2017).
cancer (continued). "CXCR4-mediated imaging in BC has not been successful up to date which might be caused by limited CXCR4 expression at the cell surface (necessary for radiotracer binding) or high CXCR4 expression in cancer stem cells of which only limited numbers are available in different BC subtypes." (PMID 28134770, 2017). "In the gene expression analysis of the orthotopic cancer cells by a single-cell multiplex real-time quantitative reverse transcription PCR followed by flow cytometric analysis, restrained cellular proliferation was associated with downregulation of the chemokine receptor CXCR4." (PMID 26083776, 2015). "CXCL12, a chemokine secreted by nerves, mediates the chemoattraction of CXCR4‐positive cancer cells, facilitating their migration toward nerves via a concentration gradient." (PMID 41556039, 2026). "The F_6 CCL19+ fibroblasts have been shown to interact with T-cells via CXCL12/CXCR4 and F_8 MMP1+ myofibroblasts (myoF) have recently been linked to an immunosuppressive neighborhood in cancer." (PMID 41438752, 2025). "Among these agents, [68Ga]Ga-pentixafor stands out, having been safely used in over 1,000 patients to image CXCR4 expression in multiple cancers." (PMID 39753364, 2025). "The CXCR4/CXCL12 axis is heavily connected to cancer metastasis, as it is involved in several steps: adhesion, invasion, cell proliferation, and survival." (PMID 40142155, 2025). "The results of the in vitro experiments reveal that TGF-β1 secretion by CAFs contributes to the increased CXCR4 expression in cancer-bearing dogs." (PMID 40849508, 2025). "Studies have demonstrated that increased CXCR4 expression enhances oligomerization and basal activity in immune and cancer cells." (PMID 40012038, 2025). "Since CXCR4 is overexpressed in more than 20 cancer types, various antagonists, mainly small molecules, peptides and antibodies, have been developed to target this receptor, many of which have reached clinical trials." (PMID 40307933, 2025). "The role of CXCR4 in cancer is much broader, given that it has been identified as a cancer marker to promote cancer cell migration and invasion." (PMID 41027939, 2025). "Several monoclonal antibodies (mAbs) targeting CXCR4 have been developed for therapeutic use, particularly in cancer treatment." (PMID 40307933, 2025). "In NSCLC, cancer-associated fibroblasts produce SDF-1, which, upon binding to CXCR4, enhances the epithelial–mesenchymal transition and invasion capacity of cancer cells." (PMID 40136462, 2025). "For example, celastrol inhibits the expression of CXCR4 to block the invasion and metastasis of cancer cells." (PMID 40391077, 2025). "In fact, several CXCL12—CXCR4 antagonists have been developed, which have shown encouraging results in anti-cancer activity both in in vitro and in vivo studies." (PMID 39859358, 2025). "has shown that DPP-4I promotes epithelial-mesenchymal transition through the CXCL12/CXCR4/mTOR axis, thereby inducing cancer progression and metastasis." (PMID 40040724, 2025). "This signaling network has established CXCR4 as a promising therapeutic target across various pathological conditions, including cancer and inflammatory disorders." (PMID 40143176, 2025). "Another key function of CXCR4 in NSCLC is its role in maintaining cancer stem cell (CSC) populations." (PMID 41149503, 2025). "Dysregulation of the CXCR4 signaling pathway can contribute to cancer growth, invasion, metastasis, and angiogenesis, underscoring its significance in cancer progression, hematopoietic stem cell transplantation, and immune-related diseases." (PMID 40430547, 2025). "In fact, CXCL12 expression levels are increased at sites of metastasis such as the brain, bone marrow, lung, and liver, so cancer cells can exploit the CXCR4/CXCL12 axis to establish distant organ metastasis." (PMID 40142155, 2025).
cancer (continued). "Other features of the CXCR4/CXCL12 signalling pathway include being a contributor to drug resistance by enriching the cancer stem cells (CSCs) and creating an immunosuppressive surrounding microenvironment." (PMID 41002447, 2025). "CXCR4, a chemokine receptor, plays a pivotal role in cancer progression, metastasis, and CSC maintenance through signaling pathways such as PI3K/AKT and JAK/STAT." (PMID 39753364, 2025). "CXCR4+ cancer cells easily migrate where CXCL12 is highly expressed, towards organs such as the lungs, lymph nodes, and bones, which represent the most common metastasis sites." (PMID 40142155, 2025). "During the process of cancer metastasis, the expression of CXCR4 can be increased, resulting in enhanced signalling pathways." (PMID 40342960, 2025). "This interaction can impact the CXCL12/CXCR4 signaling pathway, which is crucial for cancer cell migration and invasion." (PMID 40426863, 2025). "Elevated ROS levels can activate various transcriptional programs involved in cancer progression, including the upregulation of chemokine receptors such as CXCR4." (PMID 40362664, 2025). "Multiple miRNAs that regulate CXCR4 expression have been identified to show potential for cancer therapies." (PMID 40307933, 2025). "On the other hand, C-X-C- chemokine receptor type 4 (CXCR4) plays a crucial role in cancer cell metastasis." (PMID 40608162, 2025). "The MIF–CD74+CXCR4 axis, in particular, appears to drive inflammation-induced malignant transformation and cancer metastasis." (PMID 41008548, 2025). "The interaction of MIF with its receptors (CD44, CD74, CXCR4) are known drivers in late stage MM and other cancers and are involved in a variety of mechanisms, including homing to BM, pro-tumoral M0 macrophage differentiation and resistance to therapy." (PMID 41056512, 2025). "In conclusion, we have successfully applied nanobody labeling combined with TR-FRET to reveal the presence of endogenous CXCR4 oligomers opening new avenues to study its oligomerization in a disease context, e.g., in cancer." (PMID 41402431, 2025). "The CXCL12/CXCR4 axis facilitates the migration and invasion of cancer cells to distant organs, particularly the liver and lungs, which are common sites of metastasis in CRC patients." (PMID 40426863, 2025). "The CXCL12/CXCR4 axis is particularly significant in PDAC,as CXCR4 is overexpressed in cancer cells while its ligand, CXCL12, is upregulated in dorsal root ganglia (DRG)." (PMID 40981722, 2025). "CXCR4 has been shown to form high-order oligomers, or nanoclusters, which are essential for its full activation in T cells and cancer cells." (PMID 40012038, 2025). "Despite extensive research on the role of miR-216a-5p in PDAC and other types of cancer, its potential connection with PaCSCs and their associated markers CD44/CD24/CxCR4 and ALDH1 remains unexplored." (PMID 40243417, 2025). "As a chemokine receptor, CXCR4 promoted cancer cell growth, metastasis, and invasion in various cancers." (PMID 41473685, 2025). "Cancer cells interact with the bone marrow stroma via signaling molecules such as CXCL12/CXCR4, and by doing so they can occupy the bone marrow niche of hematopoietic stem cells, and then proliferate or become dormant." (PMID 40224177, 2025). "CXCR4 overexpression is usually correlated with poor prognosis and often associated with metastasis, that depends on the CXCL12-mediated promotion of cancer stem cells migration and invasion." (PMID 40307933, 2025). "NF-κB in cancer cells promotes angiogenesis by increasing the expression of C-X-C motif chemokine receptor 4 (CXCR4) and CXCL8/interleukin-8 (IL-8)." (PMID 40597301, 2025). "C-X-C chemokine receptor type 4 (CXCR4) secreted by cancer cells induces chemotaxis of CTM toward distant organs that serve as metastatic targets." (PMID 41429896, 2025).
cancer (continued). "Further studies examining the relationship between serum TGF-β1 concentration, CXCR4 expression in peripheral circulation T cells of cancer-bearing dogs will provide valuable insights." (PMID 40849508, 2025). "The α-SMA+ CAFs can promote the generation and proliferation of CD44+CD24− breast cancer stem cells by secreting CXCL12 that activates CXCR4 on cancer cells." (PMID 39780187, 2025). "The presence of CXCR4 oligomers in cancer cell lines can be due to receptor overexpression in pathological conditions." (PMID 41402431, 2025). "Bone is a common site of CXCR4-positive cancer metastases probably attracted by the elevated concentration of the natural CXCR4 ligand SDF-1 in the bone marrow." (PMID 41295054, 2025). "Studies on GPR15LG’s impact on various immune cell subsets and cancer cell types to clarify its broader role in CXCR4 signaling and its potential as a therapeutic target are highly warranted." (PMID 40394646, 2025). "Several liposomes have been surface-decorated with CXCR4-specific peptide agonists and antagonists to selectively deliver encapsulated antitumoral molecules to CXCR4+ cancer cells." (PMID 40307933, 2025). "In recent decades, a diverse catalog of CXCR4-specific ligands, including both receptor agonists and antagonists, has been developed, each of them offering unique therapeutic potential for cancer treatment and/or targeted drug delivery." (PMID 40307933, 2025). "In the primary cultures established from these two types of cancer, we used flow cytometry to measure the proportion of the cancer stem cell population expressing CD 133 and CXCR4 on its surface." (PMID 40433700, 2025). "Again, the CXCR4/CXCL12 axis promotes chemo-resistance, and chemotherapy can upregulate CXCR4/CXCL12 expression in multiple forms of cancer." (PMID 40142155, 2025). "Flow cytometry and fluorescence microscopy analysis revealed that JM173 mediated the specific targeting of CXCR4-overexpressing cancer cells and the cellular uptake and subsequent delivery of active C3 Rho-inhibiting enzyme into their cytosol." (PMID 41295054, 2025). "The system also enriched cancer stem-like properties, with higher expression of stemness-associated genes (CD24, CD44, CD133, ALDHA1, CXCR4, Sox2, Oct4, Nanog, and KLF4) and expansion of CSC populations expressing (CD44, CD90, CD117, EpCAM, and CK19)." (PMID 41149589, 2025). "Future studies should explore the potential synergistic effect of CXCR4 antagonists in cancer patients with HIV infection and the role of CXCR4-targeted imaging in selecting patients who will potentially benefit from this therapy." (PMID 40075611, 2025). "Considering the increasing relevance of the CXCR4/CXCL12 axis in cancer, several effective antagonists have been discovered in the last few years, most of them using AMD3100 as a lead compound." (PMID 40142155, 2025). "Specifically, a number of CXCR4 inhibitors are already in early-phase clinical development for various cancers." (PMID 41374320, 2025). "Endogenous CXCR4 homo-oligomers are identified in native tissue and human cancer cell lines through time-resolved Förster resonance energy transfer between fluorescently labelled nanobodies." (PMID 41402431, 2025). "CXCL12 exerts its effects primarily through its receptor CXCR4, a G-protein-coupled receptor expressed on various cell types, including cancer cells." (PMID 40481962, 2025). "A key factor in MSCs’ role in cancer progression is their ability to migrate toward tumors, driven by chemotactic signals, particularly the CXCR4/SDF-1 axis." (PMID 40784879, 2025). "While only few of them have been used in the context of cancer therapies, recent biotechnological advancements using CXCR4 as a molecular target are showing significant potential to revolutionize future cancer therapies." (PMID 40307933, 2025). "This suggests a directional migration mechanism in which high CXCL12 concentrations in lymph nodes attract CXCR4-expressing cancer cells, thereby facilitating lymphatic spread." (PMID 41149503, 2025).
cancer (continued). "CK can downregulate the SDF-1/CXCR4 signaling pathway in cancer cells, thereby inhibiting the expression of PKCα and ERK protein phosphorylation, reducing the expression of MMP." (PMID 40422575, 2025). "This chemokine distribution creates a trafficking gradient that facilitates the homing and migration of CXCR4-positive cancer cells to these metastatic niches." (PMID 41002447, 2025). "Given its central role in cancer progression and metastasis, CXCR4 has emerged as a highly promising therapeutic target." (PMID 41149503, 2025). "Bidirectional communication between cancer stem cells (CSCs) and cancer-associated fibroblasts (CAFs) amplifies stemness via paracrine stimulation of the IL-6/STAT3, TGF-β/SMAD, and CXCL12/CXCR4 signaling pathways." (PMID 41439922, 2025). "LOX, for instance, modifies the extracellular matrix to facilitate cancer cell invasion, while CXCR4 promotes the migration of cancer cells to distant sites." (PMID 40563999, 2025). "CXCL12, the ligand of CXCR4 which is a chemokine secreted by stromal cells, created a gradient that directs CXCR4-expressing cancer cells toward specific sites, such as metastatic niches." (PMID 40171226, 2025). "C-X-C chemokine receptor type 4 (CXCR4) is a receptor for stromal cell-derived factor-1 (SDF-1) and is closely associated with cancer cell migration and invasion." (PMID 40519928, 2025). "Depending on the type of cancer, CSCs can be identified by a variety of surface markers, such as CXCR4, ESA, and Nestin." (PMID 40422220, 2025). "The mechanism of action of plerixafor primarily revolves around the inhibition of the CXCL12/CXCR4 axis, exerting multiple effects in cancer therapy." (PMID 40909292, 2025). "The very high level of CXCR4 expression in those cancers, compared to healthy tissues, places this receptor as an interesting marker for diagnosis but also, as a potential tool for precise targeting and selective delivery of antitumoral drugs." (PMID 40307933, 2025). "The CXCL12/CXCR4 signalling axis plays a critical, yet poorly understood, role in the maintenance and expansion of cancer stem cells (CSCs) in TNBC." (PMID 41002447, 2025). "Considering the mechanistic consequences of the features displayed by CXCR4+ cancer cells, it is expected that their derived tumors exhibit aggressive behavior." (PMID 40307933, 2025). "Given CXCR4’s significant role in cancer progression, these antagonists hold considerable promise as therapeutic agents and targeted drug delivery ligands." (PMID 40307933, 2025). "Further investigation in larger patient cohorts, as well as other cancer types, is essential to validate the prognostic and diagnostic significance of JUNB, CXCR4, and PD‐L1 in both CTCs and exosomes." (PMID 39575761, 2025). "This approach successfully eliminated CXCR4+ cancer cells in solid tumor xenograft models, inducing potent antineoplastic effect while minimizing leucocytosis and toxicity in normal CXCR4+ tissues." (PMID 40307933, 2025). "LFC131 peptide has been also used to decorate PAMAM dendrimers or chitosan nanoparticles for the targeted delivery of encapsulated doxorubicin or docetaxel into CXCR4+ cancer cells." (PMID 40307933, 2025). "Surface expression of CXCR4 on peripheral circulating canine T cells was evaluated in 10 healthy dogs and 26 dogs with epithelial malignant tumors by flow cytometry." (PMID 40849508, 2025). "The interaction of BC cells with neutrophils enhances the expression of several metastasis-associated genes in cancer cells, including TGF-β, IL-6, MMP-12, MMP-13, CXCR-4, and CXCR7." (PMID 39609700, 2024). "The analysis revealed that cancers with higher CXCR4 expression had significantly worse overall survival." (PMID 38811530, 2024).